CRP (C-reactive protein)
Diseases named in the same sentence as CRP in open-access papers (continued):
Sharing a sentence is not in itself a finding about the gene and the disease.
fibromyalgia (39 papers, 2009 to 2026). A chronic disorder of unknown etiology characterized by pain, stiffness, and tenderness in the muscles of neck, shoulders, back, hips, arms, and legs. "The level of C-reactive protein can also be associated with NcplP, as shown in a study conducted on patients with fibromyalgia in which a correlation between the C-reactive protein level and severity of pain was reported." (PMID 37372912, 2023). "Findings from this large cross-sectional study indicate the significant positive cross-sectional association of Fibromyalgia to serum CRP may be explained, in part, by factors such as BMI, comorbidity, impaired mood, and sleep disturbance." (PMID 28687081, 2017). "Findings from this large cross-sectional study indicate a significant positive cross-sectional association of Fibromyalgia to serum C-reactive protein may be explained, in part, by BMI and comorbidity." (PMID 28687081, 2017). "The introduction of highly sensitive CRP assays (hsCRP) now makes it possible to detect even subtle inflammatory activity, including subclinical processes, which may shed light on the underlying mechanisms of fibromyalgia." (PMID 38098640, 2023). "Erythrocyte sedimentation rate (ESR) test: serum levels of inflammatory markers, including ESR, CRP, NLR, and MPV, are higher in patients than in controls, which makes them of good diagnostic value in patients with fibromyalgia." (PMID 39940388, 2025). "Some studies, employing the ELISA method, have demonstrated that fibromyalgia patients often exhibit elevated levels of inflammatory markers, including C-reactive protein (CRP), which serves as a good indicator of low-grade systemic inflammation." (PMID 39996743, 2025). "Compared with controls, patients with fibromyalgia, a condition marked by widespread pain and fatigue, presented significantly elevated levels of CRP and IL-6, which correlated positively with measures of pain sensitivity and emotional distress." (PMID 41373439, 2025). "CRP has come under increasing scrutiny in recent years, as studies have repeatedly reported elevated CRP levels in fibromyalgia syndrome." (PMID 38098640, 2023). "Fatigued PR3-ANCA patients had higher rates of cognitive failure (p = 0.001) and arthralgia (p = 0.03), more females (<0.001), and higher levels of CRP (p = 0.03), with a trend also evident for fibromyalgia symptoms (p = 0.05)." (PMID 36890852, 2023). "All participants completed a comprehensive health survey (2005–2006) part of the C8 Health Project; serum levels of CRP were obtained, as was history of Fibromyalgia physician diagnosis." (PMID 28687081, 2017). "Nor was there a correlation between this adipokine with inflammation markers, although patients with fibromyalgia and overweight have a greater inflammatory status indicated by the presence of higher CRP levels." (PMID 28226002, 2017). "Prospective research is needed to confirm this, and better clarify the potential mediating influences on the relationship between Fibromyalgia and CRP." (PMID 28687081, 2017). "Some studies have indicated that CRP concentrations in individuals with fibromyalgia may be influenced by comorbid conditions, such as obesity or concurrent inflammatory disorders, highly prevalent within this cohort." (PMID 39996743, 2025). "Moreover, the NLR was correlated with CRP and disease activity scores in both Fibromyalgia and Axial Spondyloarthritis." (PMID 40564216, 2025). "FM: Fibromyalgia; FAST: Fibromyalgia assessment screening tool; CRP: C-reactive protein; ESR: Erythrocyte sedimentation rate; DAS28: Disease activity score for 28 joints; HAQ score: Health assessment questionnaire score; DMARDs: disease-modifying antirheumatic drug." (PMID 39109111, 2024). "Despite differences in pain threshold, CRP levels and sleep problems between RA patients with fibromyalgia and those without fibromyalgia, associations between these variables did not change when patients with fibromyalgia were excluded." (PMID 19874580, 2009).
fibromyalgia (continued). "Fibromyalgia was associated with several disease/work outcomes, including higher disease activity, lower quality-of-life, and less employment although without association to swollen joints/CRP." (PMID 42176050, 2026). "The association with ASDAS ID was present also in the multivariable models including TNFi use at 1 year, symptom duration, HLA-B27 positivity, sex, age, CRP level at baseline, BASDAI score at baseline and presence of fibromyalgia." (PMID 40833778, 2025). "None of the other variables reached significance: FACIT-F (p = 0.7), PASI (p = 0.8), CRP (p = 0.1), ferritin (p = 0.2), HADS-D (p = 0.1), smoking exposure in pack-years (p = 0.2), age (p = 0.5), BMI (p = 0.1), sex (p = 0.06), or fibromyalgia (p = 0.3)." (PMID 41463039, 2025). "In Fibromyalgia patients, the NLR was positively correlated with CRP and FIQR scores, though with a small effect size (r = 0.14 and r = 0.15, respectively)." (PMID 40564216, 2025). "The results showed significant improvements in the ABCT group Fibromyalgia Impact Questionnaire (FIQ) and a decrease in BDNF, CRP, and pro-inflammatory composite compared to the RT group." (PMID 36231406, 2022). "CRP and TNF-α have also been found to be significantly higher in individuals with fibromyalgia compared to healthy controls and have been found to correlate positively with pain and fatigue." (PMID 32878326, 2020). "The selected subject is a 59 y/o female patient with clinical diagnosis of fibromyalgia, which was tested rheumatoid factor negative, CRP < 5 mg/L, with no signs of erosion in the joints of the hands (X-ray analysis)." (PMID 35892489, 2022). "Further, CRP levels did not significantly differ according to clinical characteristics, fibromyalgia, medication overuse, preventive treatment, and classes of preventive treatment medications." (PMID 36313504, 2022). "Mean CRP was higher among participants reporting Fibromyalgia than those without (5.54 ± 9.8 vs.3.75 ± 7.2 mg/L, p < .0001))." (PMID 28687081, 2017). "However, not all individuals with fibromyalgia manifest elevated CRP levels; in fact, the extent of elevation can differ markedly across patients." (PMID 39996743, 2025).
paroxysmal AF (39 papers, 2010 to 2025). "It has been demonstrated that colchicine is an effective and safe agent for preventing early AF recurrences after pulmonary vein isolation in patients with paroxysmal AF, associated with reduced CRP and IL-6 levels." (PMID 30185438, 2018). "Statins reduced the incidence of paroxysmal AF with a concomitant decrease in C-reactive protein levels, which are believed to be a risk factor for AF." (PMID 26248619, 2015). "In addition, patients with paroxysmal AF with the minor allele of SNPrs2106261 (TT + TC) had lower levels of C reactive protein(CRP), neutrophil/lymphocyte (N/L) ratios, and interleukin 6 (IL-6) expressionthan patients with the CC type." (PMID 39076272, 2023). "Additionally, Watanabe and colleagues reported that CRP levels correlated with larger left atrial diameter in patients with paroxysmal AF, which is also a recognized risk factor for AF." (PMID 29197340, 2017). "In a different study, the sole predictor of elevated CRP was the occurrence of AF; patients with paroxysmal AF had raised CRP levels only during episodes of AF." (PMID 39879166, 2025). "Plasma concentrations of CRP and CCL2 were significantly higher in patients with AF than in those with a sinus rhythm; however, CRP was elevated only in patients with permanent AF, whereas CRP was normal in patients with paroxysmal AF." (PMID 38541078, 2024). "The elevation was associated with the burden of AF, and patients with permanent AF had higher CRP levels compared with paroxysmal AF." (PMID 37834958, 2023). "Both permanent and paroxysmal AF groups had higher CRP levels compared with controls in the same study." (PMID 37834958, 2023). "This is also supported by the data that inflammatory factors statistically differ between AF categories: in paroxysmal AF, the CRP content is lower than persistent AF, but statistically significantly higher than in healthy people." (PMID 36013520, 2022). "A high level of CRP has been observed in patients with paroxysmal AF, and even a higher level of CRP is observed in patients with persistent AF." (PMID 35492601, 2022). "Estimated GFR was lower in patients with persistent AF compared with SR (p = 0.009) and C-reactive protein was higher in patients with paroxysmal AF compared with SR (p = 0.03); levels of both markers were similar in patients with paroxysmal and persistent AF." (PMID 27627677, 2016). "Our aim was to study the process in paroxysmal AF (PAF) by measuring plasma concentrations of high-sensitivity C-reactive protein (hs-CRP), serum amyloid A (SAA) and fibrinogen in dynamics." (PMID 28197262, 2016). "AF patients groups had higher CRP levels compared with control group and CRP level in persistent AF group was further higher than paroxysmal AF group (all P < 0.001)." (PMID 25810125, 2015). "Marked increase in CRP level in persistent AF when compared with paroxysmal AF suggests that inflammation has a more significant role in determining the continuity in AF process rather than a triggering role." (PMID 24712763, 2014). "Patients with persistent AF had larger left atrial diameter than patients with paroxysmal AF while other variables including baseline and 6 months hs-CRP were similar." (PMID 22957001, 2012). "Xu Baozhen study found that acupuncture combined with Wenxin granule could increase the conversion rate of paroxysmal AF and reduce the ventricular rate and the levels of CRP and brain natriuretic peptide and BNP in blood." (PMID 39612438, 2024). "In addition, in cases of permanent AF, we expected to find more significant levels of high-sensitivity C-reactive protein (hs-CRP) than in paroxysmal AF." (PMID 38203704, 2023). "In patients with paroxysmal AF, CRP level is higher during AF than during sinus rhythm." (PMID 35492601, 2022). "Moreover, patients belonging to the persistent AF group had higher CRP levels than the paroxysmal AF and the control groups, indicating the possible relationship between CRP levels and chronicity of AF." (PMID 22920484, 2012).
paroxysmal AF (continued). "Furthermore, patients with persistent AF had higher CRP levels than those with paroxysmal AF, suggesting that inflammation plays an important role in the maintenance of AF." (PMID 20537138, 2010). "Indeed, CRP levels were higher in persistent than paroxysmal AF patients." (PMID 31110819, 2019). "C-reactive protein (CRP) levels are increased in patients with persistent AF compared to controls and subjects with paroxysmal AF (PAF), thus suggesting a possible link between inflammation and AF." (PMID 22920475, 2012). "However, when patients with paroxysmal AF and permanent AF were separately analyzed, while increase in CCL2 was observed in both subgroups, CRP was only elevated in those with the permanent condition." (PMID 33765041, 2021). "Few inflammatory markers including IL-6 and Hs-CRP correlate well with the presence of AF, and therefore have a potential clinical utility in AF prediction in patients with RHD, especially paroxysmal AF." (PMID 32923332, 2020). "Moreover, we find an apparent association between the blood levels of both CK-MB and CRP, but not of leukocytes, and increasing age, specifically in patients with long-standing persistent/ permanent AF (LS-PE/PER), but not in paroxysmal AF patients (PAR)." (PMID 32072262, 2020).
Sleep apnea (39 papers, 2010 to 2025). An intermittent cessation of airflow at the mouth and nose during sleep is known as sleep apnea. "Visceral fat (0.040) and uric acid/CRP (both 0.025) also demonstrated moderate effects, suggesting their potential contribution to metabolic dysregulation in the context of sleep apnea risk." (PMID 40863567, 2025). "In the full study sample, sleep disordered breathing was associated with worse inflammatory profiles – greater levels of C-reactive protein (CRP), fibrinogen, and plasminogen activator inhibitor 1 (PAI-1)." (PMID 35130984, 2022). "A study of 316 Japanese men showed that sleep disordered breathing was associated with CRP." (PMID 24663098, 2014). "The CRP has also shown to be higher in asthmatics and patients with sleep apnea, and their prognosis has been predicted by higher CRP levels." (PMID 40662069, 2025). "A useful therapeutic implication of this study would be to understand how FeNO and CRP levels correlate or differ in asthmatic and sleep apnea patients." (PMID 40662069, 2025). "A variety of inflammatory markers such as C-reactive protein (CRP), tumor necrosis factor alpha, and interleukin-6 have been used to estimate inflammation in untreated sleep apnea." (PMID 30402295, 2018). "The inflammatory biomarkers CRP and interleukin-6 (IL-6) were found to be elevated in sleep apnea and excessive sleepiness." (PMID 29276708, 2017). "In terms of sleep disordered breathing, researchers indicated a link C-reactive protein, a marker of cardiovascular health, and sleep disordered breathing." (PMID 26213710, 2015). "Indeed several studies have been conducted on asthmatic patients and sleep apnea and their biomarkers, FeNO and CRP, separately." (PMID 40662069, 2025). "One of the reasons that increased DII scores, results in decreased sleep quality, may be because of the increase in CRP levels, that is related to increased sleep apnea." (PMID 35250226, 2022). "Notably, we took special care to ensure an equal distribution of female participants in both groups (i.e., exactly 70% in both groups) because we are aware of the differential effect of sleep-disordered breathing on serum CRP levels between sexes." (PMID 36363559, 2022). "A study conducted on about 1500 community-dwelling middle-aged men reported that an inverse association between plant-sourced dietary pattern (characterized by beta-carotene, vitamin A, lutein, and zeaxanthin) and CRP was stronger in participants with severe sleep apnoea." (PMID 31200445, 2019). "Indices of sleep apnea severity, apnea-hypopnea index and minimum oxygen saturation, were independently associated with increased levels of triglycerides, glucose as well as cholesterol/HDL ratio, uric acid and C-reactive protein." (PMID 20711453, 2010). "However, CRP > 2.1 mg/dL was modestly associated with moderate-to-severe OSA (AHI > 25) (OR = 2.05, p = 0.041), suggesting potential clinical utility as a simple, widely available screening adjunct for sleep-disordered breathing in surgical patients." (PMID 41153825, 2025). "Similarly, CRP, a marker of inflammation secreted by the liver and known to correlate with BMI, has been shown by multiple investigators to be higher in BMI-matched individuals with sleep apnea, and to also decrease with CPAP therapy." (PMID 35887329, 2022). "As for sleep apnea syndrome and more specifically OSA, CRP levels are still raised and are the result of the systemic inflammation promoted by IH." (PMID 40662069, 2025). "The present investigation is unique in its comprehensive analysis of IL-6, IL-8, IL-10, TNF-α, CRP, and S100B in a single cohort of sleep apnea patients compared to non-OSA controls in both serum and plasma." (PMID 37762178, 2023). "That is, numerous inflammatory markers, including IL-6, IL-8, TNF-α, CRP, monocyte chemoattractant protein-1 (MCP-1), ICAM, selectins, VCAM, nitric oxide, and isoprostane, are elevated in body fluids of patients with sleep apnea." (PMID 25873764, 2015).
Sleep apnea (continued). "Additionally, smokers exhibited markedly elevated CRP (10.32 ± 11.69 mg/dL) and ERS (26.20 ± 19.55 mm/h), compared to non-smokers, along with higher mean AHI and ODI scores, reflecting a greater inflammatory burden and more severe sleep-disordered breathing." (PMID 40428013, 2025). "Shinji measured the plasma levels of inflammatory factors such as hypersensitive C-reactive protein(hs-CRP), IL-6, and TNF-α in 40 patients with sleep apnea syndrome and found that these inflammatory factor levels were correspondingly elevated in patients with sleep apnea syndrome." (PMID 39799348, 2025). "The 1,216 individuals without CRP or RDW values were younger, more likely to be African American, less likely to have a sleep apnea diagnosis, and less likely to get 7-8 hours sleep per night than those included in the analysis sample." (PMID 30402295, 2018).